GRAMD1B (GRAM domain containing 1B)
Description:
Cholesterol transporter that mediates non-vesicular transport of cholesterol from the plasma membrane (PM) to the endoplasmic reticulum (ER) (By similarity). Contains unique domains for binding cholesterol and the PM, thereby serving as a molecular bridge for the transfer of cholesterol from the PM to the ER (By similarity). Plays a crucial role in cholesterol homeostasis in the adrenal gland and has the unique ability to localize to the PM based on the level of membrane cholesterol (By similarity). In lipid-poor conditions localizes to the ER membrane and in response to excess cholesterol in the PM is recruited to the endoplasmic reticulum-plasma membrane contact sites (EPCS) which is mediated by the GRAM domain (By similarity). At the EPCS, the sterol-binding VASt/ASTER domain binds to the cholesterol in the PM and facilitates its transport from the PM to ER (By similarity). Also mediates cholesterol transfer from lysosomes to endoplasmic reticulum through interaction with NPC1.
Synonyms: KIAA1201; LAMb; LINC01059
Tractability: Antibody: UniProt places it where antibodies can reach, with high confidence; its Gene Ontology location is reachable by antibodies, with high confidence; UniProt predicts a signal peptide or a membrane-spanning region; the Human Protein Atlas places it where antibodies can reach. PROTAC: ubiquitination databases record sites on it; its protein half-life has been measured.
Gene: Protein-coding gene on chromosome 11 (123,358,251 to 123,627,774, forward strand). Ensembl gene ENSG00000023171.
Subcellular location: Endoplasmic reticulum membrane; Cell membrane
Subcellular location (Human Protein Atlas): Endoplasmic reticulum; Plasma membrane; Vesicles
Gene Ontology:
Molecular function: cholesterol transfer activity; cholesterol binding; phosphatidic acid binding; phosphatidylserine binding
Biological process: lysosome to ER cholesterol transport; cholesterol homeostasis; intracellular cholesterol transport; intracellular sterol transport
Cellular component: endoplasmic reticulum; endoplasmic reticulum membrane; endoplasmic reticulum-plasma membrane contact site; membrane; plasma membrane; organelle membrane contact site
Genetic constraint (gnomAD): Loss-of-function variants: 19 observed, 38.9 expected, observed/expected ratio (o/e) 0.49, 90% interval 0.34 to 0.72. The upper end of that interval is the gene's LOEUF score, 0.72, which puts it in group 2 of 6, group 1 being the genes least tolerant of losing a copy. Missense variants: 526 observed, 602.24 expected, observed/expected ratio (o/e) 0.87, 90% interval 0.81 to 0.94. Synonymous variants: 263 observed, 239.1 expected, observed/expected ratio (o/e) 1.1, 90% interval 0.99 to 1.22.
Homologues: Orthologues: chimpanzee GRAMD1B (99% identical), dog GRAMD1B (97% identical), mouse Gramd1b (97% identical), macaque GRAMD1B (97% identical), rat Gramd1b (97% identical), rabbit GRAMD1B (96% identical), pig GRAMD1B (94% identical), guinea pig GRAMD1B (94% identical), zebrafish gramd1bb (75% identical), tropical clawed frog gramd1b (74% identical), zebrafish gramd1ba (72% identical), Drosophila melanogaster GramD1B (34% identical), and 1 more. Paralogues in human: GRAMD1A (38% identical), GRAMD1C (32% identical), GRAMD2B (12% identical), GRAMD2A (9% identical).